INS (insulin)
Diseases named in the same sentence as INS in open-access papers (continued):
Sharing a sentence is not in itself a finding about the gene and the disease.
Insulin resistance (continued). "Numerous studies in humans have found circulating plasma levels and visceral adipose gene expression of omentin to be negatively correlated with BMI, fasting insulin, and measures of homeostatic model assessment of insulin resistance (HOMA-IR)." (PMID 31533709, 2019). "High SUA directly induces insulin resistance by impairing glucose tolerance and inhibiting insulin signaling in vivo and by inducing oxidative stress in vitro." (PMID 31565055, 2019). "Type two diabetes mellitus (T2D) is a complex disease caused by multiple genetic and environmental factors with an overarching problem of insufficient insulin to meet the level of insulin resistance." (PMID 31184304, 2019). "Intracellular enzyme activity evaluation and insulin resistance models were used for validating the function of the target proteins on the downstream insulin signaling pathways." (PMID 30871060, 2019). "In a mouse model of uncompensated obesity-related insulin resistance the db/db mice, administration with curcumin (1.5 g/kg b.w./day) resulted in, significantly reduced serum glucose and HbA1c levels and increased insulin levels." (PMID 31881654, 2019). "RA treatment resulted in a significant decrease in GLU, INS and HbAc1 level, and insulin resistance according to the HOMA-IR index, OGTT and ITT, indicating its significant hypoglycemic activity." (PMID 31887996, 2019). "The FOXO and CREB families have key features for the integration of insulin production and insulin resistance signaling with glucose and lipid metabolism." (PMID 31456815, 2019). "The results of the oral glucose tolerance test (OGTT) and insulin sensitivity test (IST) showed a high level of insulin resistance in the FLHS model." (PMID 31300671, 2019). "Insulin resistance (IR) is characterized by a series of pathophysiological changes that lead to decreased sensitivity to insulin." (PMID 31461405, 2019). "The MUHO group was found to have higher insulin and homeostatic model assessment of insulin resistance (HOMA-IR) levels as compared to the MHO group." (PMID 31623319, 2019). "The upper quartile (Q4) border value of 2.40 nM was equal to the upper value of the normal range of insulin c-peptide, indicating that 25% of the patients had c-peptide values compatible with insulin resistance." (PMID 31703648, 2019). "TNFα stimulates lipolysis through attenuation of the insulin antilipolytic activity, increasing the release of free fatty acids, which are the major determinants of hepatic insulin resistance (IR) and lipogenesis, which culminates in NAFLD." (PMID 30813339, 2019). "A decrease in metabolic substrate oxidation appears as a primary defect, which, by triggering a cascade of events culminating with the intracellular accumulation of the diacylglycerol and ceramide, hampers insulin signalling and promotes insulin resistance." (PMID 31130874, 2019). "In order to do this, we investigated the levels of total fasting BA, fasting insulin, homeostasis model assessment of insulin resistance (HOMA-IR), and fasting blood glucose in severely obese patients at 7 and 30 d after laparoscopic SG." (PMID 31766784, 2019). "HFD-fed mice had significantly higher levels of fasting glucose, fasting insulin, and insulin resistance index HOMA-IR compared with control ND-fed mice." (PMID 31866871, 2019). "GK rats were obtained via repetitive selection of breeding of glucose-intolerant Wistar rats exhibiting peripheral insulin resistance and defective insulin secretory function." (PMID 31871464, 2019). "According to the investigation, TUDCA and PBA modulate obesity-related insulin resistance by reverting ERS and associated biomarkers, thus improving insulin action (NCT00771901)." (PMID 31551782, 2019). "In this way, through mechanisms involved in inflammation they contribute to insulin resistance and/or a reduction in insulin secretion." (PMID 30922303, 2019).
Insulin resistance (continued). "Deletion of the SH2B1 gene in mice has been shown to result in a severe leptin resistance, obesity, insulin resistance, and T2D, demonstrating its critical role for the maintenance of normal body weight, insulin sensitivity, and glucose metabolism." (PMID 30651891, 2019). "Insulin resistance is characterized by a decrease in insulin‐stimulated glucose uptake in adipocytes and muscle cells, as well as by a blunted insulin‐stimulated repression of hepatic glucose production." (PMID 31423716, 2019). "In insulin resistance conditions, the antilipolytic effect of insulin on adipose tissue is decreased." (PMID 31949886, 2019). "The pro-inflammatory cytokines stimulate insulin resistance by inhibiting insulin signal transduction (De Luca and Olefsky, 2008 ▶)." (PMID 30984581, 2019). "As insulin resistance becomes more severe, greater stresses are placed on the β-cells to increase their insulin output." (PMID 31258514, 2019). "Compared to ZLC, ZOC exhibited increased body weight, epididymal and retroperitoneal fat pad masses, fasting glucose, fasting insulin and insulin resistance (assessed by HOMA-IR) (p < 0.05)." (PMID 30909895, 2019). "During insulin resistance in skeletal muscle, accumulation of intramyocellular lipid and inflammation impairs the insulin mediated glucose uptake in the skeletal muscle." (PMID 30854003, 2019). "Given that skeletal muscle is characterized as a major tissue for insulin-mediated glucose disposal, skeletal muscle cell is an appropriate model to explore natural food component with potential application against insulin resistance." (PMID 29955954, 2019). "Induction of GLP-1 induction onto immunocompetent hosts showed increased insulin secretion, and insulin resistance indicates a clinical potential of developing a safe therapeutic approach." (PMID 31687377, 2019). "Pancreatic beta cells compensate by increasing the production and secretion of insulin, but when such compensation fails, insulin resistance will progress to type 2 diabetes (T2D)." (PMID 31195596, 2019). "Long-term ingestion with a high-caloric diet interferes with insulin signalling pathways, leads to the increase in peripheral insulin resistance and immune disorders (Cancello and Clément 2006)." (PMID 30840227, 2019). "In the cohort of patients with insulin resistance, both the eNOS and p38 expression were decreased compared to the insulin sensitive cohort." (PMID 30987646, 2019). "We have previously reported that the risk of type 2 diabetes, early impaired glucose tolerance, and insulin resistance can be predicted using fasting levels of adiponectin, leptin, and insulin." (PMID 31379415, 2019). "The three main targets of insulin; the liver, muscles and adipose tissue; are also the major sites of insulin resistance in the body." (PMID 31516543, 2019). "Cell-based studies in HepG2 hepatocellular carcinoma cells revealed that hepassocin can block insulin signaling and induce insulin resistance through an ERK1/2-dependent signaling pathway." (PMID 31736870, 2019). "After the 8-week AIT intervention, blood glucose parameters and the lipid profile were regulated, insulin resistance was reduced, and insulin sensitivity increased (P < 0.05)." (PMID 31249632, 2019). "In the present study, a significant condition difference was found for the Matsuda Index and HOMA-IR, indicating that a pulse-based diet, compared with typical hospital diet, improved insulin sensitivity and prevented insulin resistance during 4-day bed rest." (PMID 31461862, 2019). "An additional 41 genes associated with Mendelian forms of metabolic disease such as congenital lipodystrophy, insulin resistance and known regulators of adipocyte differentiation and insulin signaling were selected." (PMID 30940487, 2019). "It has been proposed that the decrease in insulin sensitivity precedes the impairment of b-cell function, and that the impairment of b-cells to compensate for insulin resistance is a late phenomenon." (PMID 31615167, 2019).
Insulin resistance (continued). "Although T1D can be corrected by insulin administration, over time T1D patients can develop insulin resistance that hinders glycemic control." (PMID 30809106, 2019). "The elevated insulin levels in both ob/ob−/− groups at the end of the study in combination with increased HbA1c compared to lean animals are indicative of insulin resistance typical for ob/ob−/− mice." (PMID 30732594, 2019). "Insulin resistance is manifested by a decrease in insulin-stimulated glucose transport and by altered hepatic glucose output, mainly via the IRS/PI-3-kinase/PKB signaling arm." (PMID 31551782, 2019). "ROS was shown to induce insulin resistance in adipose tissue, skeletal muscle, and hepatocytes by impairing insulin signaling." (PMID 30744071, 2019). "The homeostasis model assessment (HOMA) was developed to provide a measure of peripheral insulin resistance from fasting glucose and insulin." (PMID 31998762, 2019). "High levels of CRP are also involved in the production of adhesion molecules, namely, E-selectin, ICAM-1, and VCAM-1, which play a role in vascular endothelial dysfunction, insulin transport reduction, and peripheral insulin resistance." (PMID 31485456, 2019). "Because insulin signaling plays an important role in β-cell proliferation responding to peripheral insulin resistance, the finding of β-cell insulin resistance reveals a novel mechanism of β-cell decompensation in T2D." (PMID 31311313, 2019). "IFG indicates impaired first-phase insulin secretion and reduced hepatic insulin sensitivity, whereas IGT suggests markedly peripheral insulin resistance and defective second-phase insulin secretion, contributing to prolonged defects." (PMID 31052480, 2019). "According to Kahn and Valdez, a fat-rich diet can generate free fatty acid deposition in the pancreas; reduce insulin secretion, inducing insulin resistance, or hyperglycemia." (PMID 31830056, 2019). "Pregnancy is the ultimate indicator of infertility treatment and insulin resistance (IR) is a pathological condition in which cells fail to respond normally to the insulin." (PMID 31511054, 2019). "This insulin resistance led to significant deterioration of insulin signalling markers IR, PI3K, GLUT3 and GLUT4 (p < 0.01)." (PMID 31635074, 2019). "Hyperglycemia is known as a natural occurring and very potent factor in promoting β cell replication, which can provide an increased source of insulin to combat insulin resistance/glucose intolerance." (PMID 31557884, 2019). "AngII-induced insulin resistance is relevant to ROS, which can impair insulin signaling by decreasing phosphorylation of IRS1 and Akt and translocation of GLUT4 to the plasma membrane." (PMID 31093312, 2019). "Insulin resistance refers to the decline in efficiency of insulin to promote glucose uptake and use for various reasons, and then the compensatory hyperinsulinemia happens." (PMID 30621321, 2019). "Increased PTP1B activity attenuates insulin signals and results in insulin resistance, implying that downregulation of PTP1B activity would theoretically enhance insulin sensitivity." (PMID 30875760, 2019). "The following disturbances: systemic inflammation, defects in insulin signaling pathway, and pancreatic β-cells dysfunction, are engaged in both insulin resistance and T2DM development." (PMID 30959886, 2019). "Studies have shown that flavonoids increase insulin secretion, reducing insulin resistance, and inhibit hormone-sensitive lipase activity." (PMID 32095041, 2019). "Our study revealed that propolis supplementation decreased the levels of blood postprandial glucose and serum insulin levels, as well as, decreased insulin resistance in T2DM patients." (PMID 31086222, 2019). "The resulting increase in insulin resistance, moreover, requires eight times the normal amount of insulin volume to maintain postoperative blood glucose at normal levels." (PMID 31083704, 2019).
Insulin resistance (continued). "IR can also develop in the liver, known as hepatic insulin resistance, which is defined as impaired insulin signalling affecting the liver." (PMID 31499737, 2019). "Curcumin and rutin are well-known insulin sensitizers that improve insulin resistance and lower blood sugar levels by oral administration." (PMID 31067805, 2019). "For patients with insulin resistance, the islets of Langerhans are stimulated to promote insulin secretion to overcome the defect in plasma glucose absorption and to reduce glucose generation in liver." (PMID 30642126, 2019). "After establishing the model, we examined the effects of GRE on glucose tolerance and insulin sensitivity by performing oral glucose tolerance tests (OGTTs) and calculating Homeostatic Model Assessment of Insulin Resistance (HOMA-IR) in OBIR rats." (PMID 30717198, 2019). "In comparison, we have used 100 nm insulin which generated insulin resistance after 30 min of treatment subsequently increasing levels of total and phospho-tau." (PMID 31427921, 2019). "The modulatory anti-diabetic effects of flavonoids reduce apoptosis and insulin resistance and enhance insulin secretion and GLUT 4 translocation." (PMID 31480505, 2019). "Leptin is an adipose tissue hormone that modulates appetite and insulin activity in target cells, inducing insulin resistance." (PMID 31191339, 2019). "Macrophages express all components of insulin signaling, indicating a functional insulin signaling cascade and develop insulin resistance in the context of systemic insulin resistance." (PMID 31244863, 2019). "We have investigated how IH induces impaired insulin secretion/insulin resistance using pancreatic β cells, hepatocytes, and neuronal cells." (PMID 31013606, 2019). "In theory, reduced levels of these neuropeptides should lead to improved insulin secretion and reduced insulin resistance." (PMID 31344877, 2019). "Elevations in these cytokine levels have direct influence on insulin signal intensity, contributing to insulin resistance in the target cell." (PMID 31485456, 2019). "A recent study also showed central insulin resistance in Tau KO animals, proposing that impaired insulin signaling in the hypothalamus, the main regulator of body weight, is a possibility." (PMID 30804755, 2019). "With this in mind, further studies examining the role of primary insulin hypersecretion vs primary insulin resistance in humans, while difficult, are warranted to address this fundamental problem." (PMID 31489455, 2019). "Insulin resistance of ovarian GC and overexpression of vascular endothelial growth factor (VEGF) due to insulin stimulation are proposed to be the underlying mechanisms of poor clinical outcomes." (PMID 31970309, 2019). "The insulin shortage and insulin resistance in T1DM and T2DM, respectively, lead to suppression of PI3K/AKT signaling and, consequently, to cardiac dysfunction." (PMID 31572181, 2019). "She had severe insulin resistance, both based on fasting glucose and insulin concentrations (HOMA-IR) and on glucose and insulin concentrations during OGTT [Insulin Resistance (Belfiore) Index] despite clinical features of lipoatrophy." (PMID 31583022, 2019). "Adipose tissue (AT), which is insulin-sensitive, is considered a key regulator of the systemic metabolism and its deregulation encompasses insulin resistance, dyslipidemia, and/or glucose intolerance." (PMID 31888081, 2019). "Both the HFa and HFr group rats showed higher blood pressure, blood sugar, insulin, triglyceride, and cholesterol, as well as increased insulin resistance (increased HOMA-IR), compared with the control rats, by the end of the 15-week feeding period." (PMID 31558158, 2019). "Catalase (CAT), glutathione peroxidase (GPx), superoxide dismutase (SOD), malondialdehyde (MDA), fasting blood sugar (FBS), insulin, and homeostatic model assessment for insulin resistance (HOMA-IR) were measured in their blood samples." (PMID 31163689, 2019).
Insulin resistance (continued). "In mice fed with a high fat diet, catalpol (100 mg/kg, p.o. for four weeks) reduced insulin resistance as evidenced by the reductions in fasting blood glucose and plasma insulin concentrations and the increased responsiveness to injected insulin." (PMID 31878316, 2019). "Chronic apelin treatment (two to four weeks) improves insulin sensitivity, lowers blood glucose levels, and protect the animals from hyperinsulinemia and glucose intolerance in mice with obesity or insulin resistance." (PMID 31718027, 2019). "HPH70 markedly lowered fasting serum insulin, suggesting a protective effect against the development of insulin resistance in obese and insulin-resistant mice." (PMID 31382619, 2019). "Whereas, NOX4 enhances insulin signaling via inhibition of PTP1B to counteract the onset of insulin resistance." (PMID 31382355, 2019). "As previously discussed, hyperinsulinemia can lead to insulin-mediated signalling and insulin resistance that promotes CRC progression and metastasis." (PMID 31831021, 2019). "The fish oil supplementation significantly decreased plasma insulin concentration and Homeostatic Model Assesment for Insulin Resistance (HOMA-IR) index and reduced content of adipose tissue biologically active lipids in comparison with HFD-fed subjects." (PMID 31013835, 2019). "In this way, insulin signaling plays a key role in glycometabolism reprogramming, and insulin resistance can promote the occurrence and development of endometrial cancer through an indirect pathway or ligand-receptor direct pathway." (PMID 31440472, 2019). "Insulin resistance was reduced as shown by an improvement in glucose and insulin tolerance and serum adiponectin." (PMID 31226166, 2019). "In order to assess insulin signaling directly, Akt phosphorylation in response to insulin administration was examined in the liver and eWAT, where HFD-induced inflammation causes local insulin resistance and changes in adipokine expression." (PMID 31387996, 2019). "The HOMA insulin resistance scores were also lowest when the dogs were on this feeding regime, which is a reflection of both low fasting glucose and insulin concentrations." (PMID 31998762, 2019). "Insulin directly modulates steroidogenesis in ovarian cells, and insulin resistance plays an important role in the pathogenesis of PCOS." (PMID 31417493, 2019). "A disruption in the transmission of insulin signaling, recognized as insulin resistance, is the main pathological process leading to T2DM, and is also an underlying pathology of other disorders included under the spectrum of “metabolic syndrome”." (PMID 31234331, 2019). "Two basic pathological defects are observed in the pathogenesis of this disease, namely, reduced insulin secretion and reduced sensitivity to this hormone in its target tissues, i.e., insulin resistance (IR)." (PMID 31354904, 2019). "During late gestation (third trimester), GDM patients have insulin resistance and lower insulin secretion rates and glucose uptake rates." (PMID 31558153, 2019). "Plasma insulin levels were markedly increased in the HFD group, demonstrating that HFD causes insulin resistance." (PMID 30914769, 2019). "It is a prime factor in obesity and contributes to insulin resistance by decreasing insulin-stimulated glucose disposal in the skeletal muscles, which are the main consumer of glucose in vivo." (PMID 31253153, 2019). "Physiologically, a large chronic influx of fructose in the liver causes an accumulation of triglycerides and cholesterol because of its lipogenic properties, reducing insulin sensitivity, and producing insulin resistance and glucose intolerance." (PMID 31330823, 2019). "In our study, blood insulin levels were decreased, and insulin resistance was significantly improved in proportion to the AM-Ex concentration." (PMID 31137884, 2019). "Insulin dysregulation can be exacerbated if insulin resistance occurs as a counter-regulatory response to chronic post-prandial hyperinsulinemia." (PMID 30808423, 2019).